CPEB3 (cytoplasmic polyadenylation element binding protein 3)
Description:
Sequence-specific RNA-binding protein which acts as a translational repressor in the basal unstimulated state but, following neuronal stimulation, acts as a translational activator (By similarity). In contrast to CPEB1, does not bind to the cytoplasmic polyadenylation element (CPE), a uridine-rich sequence element within the mRNA 3'-UTR, but binds to a U-rich loop within a stem-loop structure (By similarity). Required for the consolidation and maintenance of hippocampal-based long term memory (By similarity). In the basal state, binds to the mRNA 3'-UTR of the glutamate receptors GRIA2/GLUR2 mRNA and negatively regulates their translation (By similarity). Also represses the translation of DLG4, GRIN1, GRIN2A and GRIN2B (By similarity). When activated, acts as a translational activator of GRIA1 and GRIA2 (By similarity). In the basal state, suppresses SUMO2 translation but activates it following neuronal stimulation (By similarity). Binds to the 3'-UTR of TRPV1 mRNA and represses TRPV1 translation which is required to maintain normal thermoception (By similarity). Binds actin mRNA, leading to actin translational repression in the basal state and to translational activation following neuronal stimulation (By similarity). Negatively regulates target mRNA levels by binding to TOB1 which recruits CNOT7/CAF1 to a ternary complex and this leads to target mRNA deadenylation and decay. In addition to its role in translation, binds to and inhibits the transcriptional activation activity of STAT5B without affecting its dimerization or DNA-binding activity. This, in turn, represses transcription of the STAT5B target gene EGFR which has been shown to play a role in enhancing learning and memory performance. In contrast to CPEB1, CPEB2 and CPEB4, not required for cell cycle progression.
Synonyms: KIAA0940
Tractability: Antibody: its Gene Ontology location is reachable by antibodies, with high confidence; the Human Protein Atlas places it where antibodies can reach. PROTAC: UniProt records ubiquitination sites on it; ubiquitination databases record sites on it.
Gene: Protein-coding gene on chromosome 10 (92,046,692 to 92,291,628, reverse strand). Ensembl gene ENSG00000107864.
Subcellular location: Cytoplasm; Nucleus; Synapse; Cell projection, dendrite; Postsynaptic density
Subcellular location (Human Protein Atlas): Cytosol; Midbody; Nucleoplasm; Plasma membrane
Gene Ontology:
Molecular function: mRNA 3'-UTR binding; protein binding; RNA binding; translation factor activity, RNA binding; mRNA 3'-UTR AU-rich region binding; mRNA regulatory element binding translation repressor activity; ribosome binding; RNA stem-loop binding; nucleic acid binding; translation regulator activity
Biological process: 3'-UTR-mediated mRNA destabilization; cellular response to amino acid stimulus; negative regulation of transcription by RNA polymerase II; negative regulation of translation; positive regulation of nuclear-transcribed mRNA catabolic process, deadenylation-dependent decay; positive regulation of nuclear-transcribed mRNA poly(A) tail shortening; long-term memory; negative regulation of cytoplasmic translation; negative regulation of cytoplasmic translational elongation; positive regulation of dendritic spine development; positive regulation of translation; regulation of dendritic spine development; regulation of postsynapse assembly; regulation of synaptic plasticity; regulation of translation; translation
Cellular component: CCR4-NOT complex; cytoplasm; neuron projection; nucleus; apical dendrite; dendrite; synapse; postsynapse; postsynaptic density
Genetic constraint (gnomAD): Loss-of-function variants: 16 observed, 41.53 expected, observed/expected ratio (o/e) 0.39, 90% interval 0.26 to 0.58. The upper end of that interval is the gene's LOEUF score, 0.58, which puts it in group 2 of 6, group 1 being the genes least tolerant of losing a copy. Missense variants: 688 observed, 787.41 expected, observed/expected ratio (o/e) 0.87, 90% interval 0.82 to 0.93. Synonymous variants: 355 observed, 331.72 expected, observed/expected ratio (o/e) 1.07, 90% interval 0.98 to 1.17.
Homologues: Orthologues: chimpanzee CPEB3 (99% identical), macaque CPEB3 (99% identical), pig CPEB3 (98% identical), dog CPEB3 (98% identical), rabbit CPEB3 (98% identical), mouse Cpeb3 (97% identical), rat Cpeb3 (97% identical), guinea pig CPEB3 (70% identical), tropical clawed frog cpeb3 (70% identical), zebrafish cpeb3 (65% identical), Drosophila melanogaster orb2 (41% identical), Caenorhabditis elegans cpb-1 (26% identical), and 1 more. Paralogues in human: CPEB2 (60% identical), CPEB4 (59% identical), CPEB1 (23% identical).
Diseases named in the same sentence as CPEB3 in open-access papers:
CPEB3 is named in the same sentence as 43 diseases in open-access papers, as found by Europe PMC text mining. Sharing a sentence is not in itself a finding about the gene and the disease. The quoted sentences say what the papers report.
hepatocellular carcinoma (17 papers, 2016 to 2023). A malignant tumor that arises from hepatocytes. "In hepatocellular carcinoma patient samples, CPEB3 was downregulated and was associated with poor prognosis and high-grade malignancy." (PMID 29850575, 2018). "Lidocaine has been reported to inhibits hepatocellular carcinoma development via regulating miR-421/CPEB3 pathway, and inhibits glioma cell proliferation, migration and invasion via regulating the circEZH2/miR-181b-5p axis." (PMID 35212616, 2022). "miR-9-5p enhances the tumorigenic ability of hepatocellular carcinoma cells by targeting CPEB3 and ESR1, but miR-9 plays a tumor suppressor role in hepatocellular carcinoma by regulating IGF2BP1, Sox11, and P21." (PMID 36421826, 2022). "Studies have found that CPEB3 is related to the tumorigenesis and development of glioma, high-grade serous ovarian cancer, colorectal cancer, hepatocellular carcinoma, and cervical cancer." (PMID 34879089, 2021). "Mir-107 and CPEB3 interaction plays an important role in the occurrence and development of hepatocellular carcinoma by regulating the EGFR signaling pathway." (PMID 34879089, 2021). "Consistent with our results, previous research found that CPEB3 represses proliferation and metastasis in hepatocellular carcinoma cells." (PMID 33146632, 2020). "In our previous work, we uncovered that CPEB3 is a novel target of miR-107 and inhibits hepatocellular carcinoma (HCC) progression." (PMID 32968053, 2020). "MiR-18a-5p is upregulated in hepatocellular carcinoma, and its overexpression significantly promotes tumor cell growth, while miR-18a-5p acts as an oncogenic factor to accelerate the malignant phenotype of hepatocellular carcinoma by inhibiting CPEB3." (PMID 37525284, 2023). "Mainly The glucose metabolism process and the development and differentiation of precursor adipocytes were regulated of miR-15a by inhibiting the formation of insulin, and miR-20b-5p promoted hepatocellular carcinoma cell proliferation, migration and invasion by down-regulating CPEB3." (PMID 36514049, 2022). "Our previous study showed that CPEB3 could inhibit the metastasis of hepatocellular carcinoma (HCC) by inhibiting the expression of MTDH." (PMID 34930897, 2021). "Abnormal expression of CPEB3 has been found in a variety of cancers, such as cervical cancer and human hepatocellular carcinoma; studies have found that miRNAs can directly target the CPEB3/EGFR axis to regulate tumor progression, but few studies are focusing on the nervous system." (PMID 34900520, 2021). "On the other hand, it has been found that CPEB3 inhibited the proliferation, migration, invasion, and apoptosis of hepatocellular carcinoma (HCC) cells, leading to G0/G1 arrest." (PMID 33506034, 2021). "To further explore the function of miR-9-5p/FOXO1/CPEB3 FFL in vivo, we built hepatoma xenografts in nude mice." (PMID 35805200, 2022). "After up regulating the expression of mir-107 in hepatoma cell lines Huh7 and HepG2, the mir-107 bound to the 3‘-UTR region of the CPEB3 transcript, and resulted in an increased expression of EGFR and phosphorylated Akt and decreased expression of p21." (PMID 34879089, 2021). "We had reported that CPEB3 is involved in hepatocellular carcinoma (HCC) progression." (PMID 32968053, 2020).
glioma (16 papers, 2016 to 2025). A benign or malignant brain and spinal cord tumor that arises from glial cells (astrocytes, oligodendrocytes, ependymal cells). "Our data suggest that loss of CPEB3 activity in high-grade gliomas is caused by expression of alternatively spliced variants lacking the B-region that overlaps with the kinase recognition site." (PMID 27256982, 2016). "Our finding that CPEB3 in high grade gliomas is expressed as a splice variant that cannot be activated by phosphorylation suggests that it might contribute to altered protein expression in these tumors and be considered an attractive target for new therapeutic strategies." (PMID 27256982, 2016). "HCG11 acts as a competing endogenous RNA by sponging miR-496, thereby upregulating cytoplasmic polyadenylation element binding protein 3 (CPEB3) in glioma cells." (PMID 41272822, 2025). "CPEB3 protein content was increasing with WHO grade while expression of active phospho-CPEB3 protein was decreasing with tumor grade in human gliomas." (PMID 38158431, 2023). "HCG11 inhibited glioma progression by modulating miR‐496 to upregulate cytoplasmic polyadenylation element binding protein 3 (CPEB3) expression." (PMID 34178684, 2021). "Previous experiments have reported the promoting role of miR-21 in glioma, and upregulation of SATB1 and CPEB3 is associated with the development and progression of glioma." (PMID 35069683, 2021). "The survival analysis further suggested the regulatory correlation: elevated FAM18A-AS1 and miR-21 were associated with poor prognosis in glioma, and low expression of BCL7A, SATB1, and CPEB3 was associated with favorable prognosis." (PMID 35069683, 2021). "CPEB3 expression appeared to be the most abundant amongst CPEBs in gliomas and present in cytoplasm and processes of astrocytic tumor cells (gemistocytes)." (PMID 27256982, 2016). "Immunohistochemical analysis of CPEBs in gliomas indicated that expression of active phospho-CPEB3 protein shows an inverse correlation with the glioma malignancy grade (right)." (PMID 27256982, 2016). "This interesting finding suggests that by alternative splicing, high-grade glioma cells achieve a deregulation of CPEB3-dependent translational control." (PMID 27256982, 2016). "In contrast to CPEB3 expression, phosphorylation of CPEB3 protein was observed mainly in low-grade gliomas (7/8 AII, 17/20 AAIII) and distinctly lower in glioblastomas (10/26 pGBM)." (PMID 27256982, 2016). "LncRNA-HCG11 can interact with the miR-496/CPEB3 axis to inhibit glioma progression." (PMID 34818353, 2021). "HCG11 modulated glioma progression through its action on the miR-496/CPEB3 axis." (PMID 33901010, 2021). "CPEB3 was the most abundantly expressed CPEB family member in human gliomas." (PMID 27256982, 2016). "Our findings indicate that phospho-CPEB3 may be considered as a marker for prolonged survival of glioma patients, especially for patients diagnosed with AII, AAIII and sGBM that share a similar molecular background." (PMID 27256982, 2016). "Accordingly, lack of active kinases cannot explain the loss of CPEB3 activation in high-grade gliomas." (PMID 27256982, 2016). "Accordingly, expression of active phospho-CPEB3 protein was a main feature of low-grade gliomas." (PMID 27256982, 2016). "Notably, reduced CPEB3 activity in gliomas may contribute to tumor progression and malignancy." (PMID 40561176, 2025). "Inversely, in glioma, HCG11 has been illustrated to limit the development of glioma in regulation of miR-496/CPEB3 axis." (PMID 34230221, 2021). "This ultimately leads to altered epigenetic marks e.g. the glioma hypermethylator phenotype (G-CIMP) Besides CPEB1, we only observed altered methylation of a few CpG sites in the CPEB3 gene." (PMID 27256982, 2016). "A lack of CPEB3 activation was observed in high grade gliomas suggestive of defective translational control in these tumors." (PMID 27256982, 2016).
glioma (continued). "In order to understand why CPEB3 protein is strongly expressed but not activated/phosphorylated in high-grade gliomas, we decided to further examine tumors with strong (intensity 3) phospho-CPEB3 expression (n = 6, AII and AAIII) and samples negative for phospho-CPEB3 (n = 7, pGBM)." (PMID 27256982, 2016).
colorectal cancer (12 papers, 2018 to 2025). A primary or metastatic malignant neoplasm that affects the colon or rectum. "We showed that colorectal cancer tissues exhibited dampened CPEB3 expression which was closely associated with poor prognosis in patients with colorectal cancer (47 vs. 62 months, P = 0.035, n=99)." (PMID 33146632, 2020). "In the present study, we confirmed that CPEB3 expression decreases in colorectal cancer tissues, a pattern that is closely associated with poor patient prognosis." (PMID 33146632, 2020). "Implications: This study identified a novel role of the RNA binding protein CPEB3 in inhibiting cell proliferation and migration as well as the underlining mechanisms in colorectal cancer cells." (PMID 33146632, 2020). "Furthermore, CPEB3 associates with tumor-related mRNAs in colorectal cancer cells, specifically targeting the 3ʹUTR of JAK1 mRNA to inhibit JAK/STAT pathways." (PMID 33146632, 2020). "In contrast, cytoplasmic polyadenylation element binding protein 3 (CPEB3) disrupts the crosstalk between colorectal cancer cells and TAMs by targeting the IL-6R/STAT3 signaling pathway, thereby inhibiting EMT." (PMID 40131539, 2025). "Down-regulation in digestive tract cancers is demonstrated, and for example CPEB3 KD increased proliferation, migration and invasion in colorectal cancer cells via the JAK/STAT pathway activation." (PMID 39696035, 2024). "The role of CPEB3 (as a tumor suppressor) has recently been demonstrated in colorectal cancer through regulation (post-transcriptional) of the JAK/STAT signaling pathway." (PMID 35885958, 2022). "Our transfection experiments to overexpress or knockdown CPEB3 in three colorectal cancer cell lines were controlled using qPCR and WB experiments." (PMID 33146632, 2020). "CPEB3 is related to tumorigenesis and has been found to be downregulated in colorectal cancer through the microarray-based high-throughput screening." (PMID 32653013, 2020). "Active JAK1 translation is induced when CPEB3 is down-regulated, causing abnormal JAK/STAT signaling activation in colorectal cancer." (PMID 33146632, 2020). "In this study, we explored the clinical, biological, and mechanical role of CPEB3 in colorectal cancer progression." (PMID 33146632, 2020). "Lower CPEB3 expression predicts shorter survival time in patients with colorectal cancer after surgical resection." (PMID 33146632, 2020). "In this study, whole-genome arrays revealed that CPEB3 overexpression in colorectal cancer cells down-regulated 226 genes by over two-fold, while up-regulating only 30 more." (PMID 33146632, 2020). "Altogether, this study revealed that colorectal cancer tissues exhibit repressed CPEB3 expression, a phenomenon that predicts poor prognosis in patients with colorectal cancer." (PMID 33146632, 2020). "We then employed qRT-PCR, IHC, and WB on a panel of human colorectal cancer tissues (n = 84) from patients undergoing surgical resection in our hospital to further confirm CPEB3 ectopic expression." (PMID 33146632, 2020). "Down-regulation CPEB3 promoted proliferation, migration, and invasion in colorectal cancer cells and vice versa." (PMID 33146632, 2020). "Mechanistically, CPEB3 performed as an RNA binding protein binding to 3ʹUTR of JAK1 mRNA to inhibit JAK/STAT pathways in colorectal cancer cells." (PMID 33146632, 2020). "In this study, we showed that CPEB3 is frequently down-regulated in colorectal cancer tissues compared with matched peri-tumoral tissues." (PMID 33146632, 2020). "As we have proved that reduced CPEB3 expression resulted in more aggressive proliferation and metastasis capacity in colorectal cancer cells and CPEB3 involved in the regulation of JAK/STAT signal pathway." (PMID 33146632, 2020). "Together, these results support conclusions from clinical data that CPEB3 is a tumor suppressor in colorectal cancer progression." (PMID 33146632, 2020).